CD4 (CD4 molecule)
Diseases named in the same sentence as CD4 in open-access papers (continued):
Sharing a sentence is not in itself a finding about the gene and the disease.
infection (continued). "In particular, the production of interferon (IFN) γ by CD4+ Th1 cells is important to control Mav infection, and mice genetically deficient in IFNγ have increased susceptibility to infection." (PMID 32582196, 2020). "Upon infection, IL-17A production by both Gal-3-deficient and wild-type neutrophils is higher than that of CD4+ T cells and is increased by the addition of recombinant IL-23." (PMID 32973776, 2020). "This was not due to these subsets contributing a higher proportion of the CD4+ T cell pool, rather these subsets were more susceptible to infection (median: 5.38% EM and 2.15% TM cells infected), consistent with heightened CCR5 expression on EM and TM cells." (PMID 32762760, 2020). "In patients infected with SARS‐CoV, the acute phase of infection is associated with a severe reduction in T cell numbers in the blood, involving a dramatic loss of CD4 and CD8 T cells in comparison to healthy control individuals." (PMID 32975374, 2020). "Our data suggest that this is linked to differential antigen-specific CD4 T cell differentiation driven by the infection." (PMID 33240275, 2020). "One of the biggest concerns of using T cells to treat HIV is the risk of infection of the infused CD4+ T-cell compartment by the reactivated virus." (PMID 32775304, 2020). "CD4+Foxp3+Tregs maintain immune homeostasis, but distinct mechanisms underlying their functional heterogeneity during infections are driven by specific cytokine milieu." (PMID 33240286, 2020). "By contrast, infection in IL-33 KO mice was associated with a significant attraction of B lymphocytes, CD4+ and CD8+ T lymphocytes, as well as NK cells on Day 60, without any clear impact on spleen weight, nor on GC area, yet ensuring parasite control." (PMID 32571430, 2020). "Here, we utilized DMS to identify Env mutations that enhance infection of cells expressing macaque CD4 and CCR5 receptors." (PMID 32098152, 2020). "Much is discussed about the events associated with the infection and its resolution and it has been suggested that CD4+ T lymphocytes mediate a protective immunity, whereas CD8+ T lymphocytes would have a pathological-cytotoxic role." (PMID 32203546, 2020). "We then investigated if the characteristics of CD161+ CD4+ T cells pre-infection were associated with HIV acquisition or disease progression." (PMID 33322496, 2020). "The infection causes depletion of parasite-specific CD4+ T cells due to apoptosis, leading to impaired T cell-mediated immunity." (PMID 33298881, 2020). "A reduction of the CD4+ T cell population is usually associated with the inability to control the infection, allowing the survival and replication of Leishmania parasites in macrophages, which can subsequently lead to increased infectibility to sand flies." (PMID 32760744, 2020). "Among those, we show that suppression of Malat1 is a hallmark of CD4+ T cell activation, but its complete deletion results in more potent immune responses to infection." (PMID 32321759, 2020). "CCR5 is not only upregulated shortly after activation, but is maintained in memory CD4+ T cells, which are highly susceptible to infection by R5‐tropic HIV‐1 strains." (PMID 32525588, 2020). "Currently, there are few quantitative studies and prediction models which show that HIV virus and reduced CD4 count increase the risk of infection with internal fixation and implant devices during orthopedic surgery." (PMID 33243159, 2020). "T-bet directly bound to and activated the expression of various mTOR-activating and metabolic genes, and Th1 cells exhibited high levels of sustained mTOR activity compared with T-bet–deficient effector CD4+ T cells throughout the course of infection." (PMID 32817333, 2020). "Many of these mutations also modestly increased infection of cells bearing human CD4 and CCR5 (up to 1.5-fold)." (PMID 32098152, 2020). "To date, most studies comparing the susceptibility of different CD4+ T cells to infection by HIV have been conducted on cells isolated from human blood." (PMID 32353080, 2020).
infection (continued). "Both progressive infection in pathogenic hosts and benign infection in vervets result in a massive acute depletion of CD4+ T cells residing in the gut during the early acute stage of experimental infection." (PMID 33158452, 2020). "Evidence suggests that HIV predisposes the host to TB by preferential infection and depletion of Mtb-specific CD4+ T cells that being CCR5high and MIP-1βlow compared with cells of other specifici-ties that are CCR5low and MIP-1βhigh." (PMID 32862519, 2020). "The susceptibility to infection shown by BALB/c mice correlates with the induction of a dominant Interleukin (IL)-4–producing CD4+ Th2 response, and to the generation of parasite-dependent IL-10 responses." (PMID 33362772, 2020). "In an experimental infection of mice which were deficient in CD4+ Th1 cytokines, IL-12, IFN-γ, TNF-α, or inducible NOS (iNOS) revealed failure to control parasite replication." (PMID 32656269, 2020). "In immunosuppressed cancer patients or transplantation recipients, a low frequency of CD161+ CD4+ T cells has been associated with increased risk of infections." (PMID 33322496, 2020). "Specifically, when NHPs are infected with a macrophage-tropic SIV capable of efficient CD4-independent entry and are immunosuppressed, the resulting infections are often highly pathogenic, with large numbers of infected macrophages." (PMID 32992787, 2020). "Depletion of CD4 T cells caused lethality in the majority of mice, which succumbed by day 10 after infection." (PMID 32669460, 2020). "Nevertheless, there is evidence that HIV-1 can infect resting CD4 T cells directly or via cell-to-cell transmission, though infection in these cells is associated with slower replication kinetics." (PMID 32318356, 2020). "A major effect of HIV-1 (herein called HIV) infections is the loss of CD4 T cells, the primary target of direct HIV infection." (PMID 32194550, 2020). "In agreement with previous studies, infection with cell-associated virus resulted in significantly higher infection rate of CD4+ T cells when compared with cell-free virus." (PMID 31919342, 2020). "The concentrations of the HIV-1 p24 protein upon stimulation by IFN-γ and infection by Nef-competent virus (HIV-1 NL4-3) or Nef-deficient virus (HIV-1 NL4-3ΔNef) were determined in lysates of CD4+ Jurkat cells by enzyme-linked immunosorbent assay (ELISA)." (PMID 33109760, 2020). "The role of CTLA4 in the pathogenesis of infection is suggested by the positive association with viral loads, and depletion of CD4 T cells." (PMID 32714317, 2020). "Notwithstanding, multivariant infection was associated with rapid CD4+ T cell decline and perturbances in the CD4+ T cell and B cell compartments compared to single variant infection, which were reversible upon control of viremia." (PMID 32886726, 2020). "In ex vivo models, macrophages, dendritic cells, and B cells isolated from peripheral blood are able to mediate trans infection, resulting in p24 accumulation orders of magnitude greater than levels associated with direct cis infection of CD4 + T cells." (PMID 33214610, 2020). "As a result of low CD4 cell count, even the normal flora of the body can cause serious infections and complications that lead to death in children infected with HIV." (PMID 32973396, 2020). "In immunocompromised patients, especially those with impaired CD4+ T cell function, pneumocystis organisms begin to proliferate in alveolar spaces and cause fatal infection if untreated." (PMID 32149364, 2020). "Multivariant infection was associated with multiple perturbations of the CD4+ T cell compartment at 0–3 months post infection, with CD4+ T cell phenotypes appearing similar between the two groups at all other time points." (PMID 32886726, 2020). "Senescence of CD4+ T cells makes ACS patients more susceptible to pathogenic infection, which can explain why chronic infection always accompanies ACS." (PMID 33269101, 2020).
infection (continued). "The primary target for productive infection is the activated CD4+ T lymphocytes, which causes significant phenotypic and functional alterations in the infected cells following HHV-6 infection." (PMID 32516328, 2020). "Bronchial brushings obtained before and 7 days after infection were therefore analyzed using a qPCR array of soluble mediator genes to screen for associations with CD4+ T cell recruitment." (PMID 31815739, 2020). "A higher number of naïve and activated CD4+ (CD4+CD44lowCD62Lhigh and CD4+ CD44highCD62Llow, respectively) T lymphocytes were observed in the lungs of AhR deficient mice at both post-infection periods studied." (PMID 32647342, 2020). "We recently conducted a CyTOF study to better understand the types of tissue CD4+ T cells that are most and least susceptible to infection by HIV." (PMID 32353080, 2020). "This suggests that the hallmark immunodeficient state in those with HIV due to loss of CD4+ cells is perpetuated by the increase in number of Tregs, further compromising the immune system and increasing the individual’s susceptibility to infection by M. tb." (PMID 32824563, 2020). "It has been shown that the cytotoxicity executed through CD4-CTLs becomes effective when CD8-CTL activity is impaired during infections in association with virus escape strategies." (PMID 33126494, 2020). "Numerous studies identified several cell populations with high susceptibility to infection, including central memory CD4+ T cells (TCM), CD4+ T memory stem (TSCM) cells, regulatory T (TREG) cells; TH17 cells, T follicular helper cells (TFH)." (PMID 32194526, 2020). "CMV-seropositivity is a potential strong confounder of this association because of the CMV-infection associated increase in the CD8 T cells count leading to a significantly decreased CD4/CD8 T-cell ratio." (PMID 32082402, 2020). "On day 5 after LM-GP66 infection, the transferred virus-specific CD4 T cells with tamoxifen-induced EZH2 deficiency were barely detectable, while vehicle-treated mice showed a robust memory CD4 T cell response upon infection." (PMID 32999031, 2020). "Seminal studies demonstrated that depletion of CD8+ T cells resulted in prolonged HCV infection and CD4+ T cell response during early phase infection is associated with clearance." (PMID 32485887, 2020). "Infection with helminths is associated with skewing of the immune system to a TH2 CD4 T cell response." (PMID 32117277, 2020). "Further, adoptive transfer of CD4+ T cells to T and B cell deficient mice is sufficient to confer protection against infection." (PMID 32655568, 2020). "To address the role of IFNAR signaling specifically in T cells during in vivo infection, we transferred CD4+ cells from Ifnar1-/- or C57BL/6 WT mice to Rag1-deficient mice (Rag1-/- mice)." (PMID 32210480, 2020). "The expansion of CD4+CD28null T cells is associated with aging, infection, and chronic inflammatory diseases." (PMID 33269101, 2020). "Depletion or ablation of CD4+ cells is enough to induce to susceptibility to infection in otherwise resistant mouse strains." (PMID 32655568, 2020). "Patients withCD4+ <100 cell/mm3 have a higher risk ofCryptosporidium infection than those with CD4+>100 cell/mm3." (PMID 32037854, 2020). "Expansion of CD4+CD28null T cells is associated with increased risk of infection and mortality, but is only present in cytomegalovirus (CMV)–seropositive individuals." (PMID 30102389, 2019). "Granuloma formation in livers of L. donovani infected mice was assessed at days 15, 30, and 56 post-infection in CD4+ T cell specific IL-4Rα deficient (LckcreIL-4Rα−/lox), wild-type littermate control (IL-4Rα−/lox) and global IL-4Rα−/− BALB/c mice." (PMID 31475014, 2019). "Human immunodeficiency virus (HIV) and simian immunodeficiency virus (SIV) infections induce a severe immune-deficient condition due to a decreased number of CD4 T cells." (PMID 31878130, 2019).
infection (continued). "In a recent study, we demonstrated that reactivation of the infection in chronically infected host is a consequence of CD8 T dysfunction caused by CD4 T cell exhaustion." (PMID 31119107, 2019). "Studies have reported that earlier stage of the infection, higher CD4 counts, and treatment with c-ART was associated with better survival of HIV positive patients." (PMID 31288761, 2019). "Such low CD4+ counts among HD patients were significantly associated with the infection with opportunistic parasites Cryptosporidium species, B. hominis, microscopridia and T. gondii." (PMID 31142275, 2019). "Both CD4+ T cell specific IL-4Rα deficient mice and wild-type control mice produced comparable amounts of IgE on days 30 and 56 post-infection." (PMID 31475014, 2019). "Infection with HIV causes significant perturbations within the immune system including CD4 T cell depletion and the induction of systemic inflammation through bacterial translocation across the gut mucosa." (PMID 31260499, 2019). "It is likely that the more robust inflammatory signaling associated with infection results in the development of a progressively more Th1 biased CD4 T cell response." (PMID 30692574, 2019). "As the major site of HIV replication is in CD4+ T cells, LNs and the gut associated lymphoid tissue are the initial and persistent targets of infection." (PMID 31552045, 2019). "TLR9 1635A/G polymorphism has also been previously studied in context of HIV infection and associates with HIV acquisition/infection, disease progression, CD4 counts and viral load." (PMID 30651082, 2019). "Such a limitation is linked, in large measure, to continuous long-term infections in CD4 + memory T cells and less frequently in mononuclear phagocytes despite both directed host antiviral immunity and ART effectiveness." (PMID 31266936, 2019). "In the context of HIV, TLR9 1635A/G polymorphism has previously been shown to associate with HIV acquisition/infection, disease progression, CD4 counts and set point viremia." (PMID 30651082, 2019). "We selected STCO1 for our analyses as this strain results in high infection rates in CD4 +T cells and shows a complete loss of NF-κB inhibition upon mutation of R45K." (PMID 30717826, 2019). "The presence of activated T cells is associated with increased susceptibility to infection; in particular, activation phenotypes of CD4+ T cells co-expressing the markers HLA-DR and CD38 and HLA-DR+CD38- cells are preferentially infected by HIV-1." (PMID 31550271, 2019). "Phenotyping of mononuclear cells isolated from blood during the chronic phase of infection showed that Rh-α4β7 treatment was associated with an increase of CCR6+/CD95- CD4- cells compared to both control groups." (PMID 31083697, 2019). "Depletion results from both direct infection and bystander loss of memory CD4+ T cells in part attributed to dysregulated IL-7/IL-7R signaling." (PMID 31507594, 2019). "CD4+ T cells from the same donors were also tested for their susceptibility to HIV-1 cis infection, either in the presence of ART drugs or when left untreated." (PMID 31304185, 2019). "In the multivariate analysis, CD4+ count was negatively associated with viral load for infections diagnosed during stage 0, stage 2, and stage 3 (multivariate linear regression; p < 0.001)." (PMID 31857582, 2019). "The following sections will outline the effects that persistent pathogenic infections or tumors have on CD4+ and CD8+ memory or “memory-like” T cell development and responses, and the interplay between the two." (PMID 31379821, 2019). "In this proof-of-concept study, we demonstrate that subclinical reactivation of CMV drives expansion of the CD4+CD28null T-cell subset that has previously been associated with increased risk of infection and mortality in AAV." (PMID 30102389, 2019). "High levels of IL-10 during the initial phases of infection due to decreased multifunctional CD4 T cells results in higher susceptibility to VL." (PMID 31024534, 2019).
infection (continued). "In another context, CD4+ counts of < 200 cells/μl were significantly associated with infection with Cryptosporidium species, C. belli and microsporidia among HIV-infected patients on antiretroviral therapy from Cameroon." (PMID 31142275, 2019). "In the absence of combined antiretroviral therapy (cART), HIV-infected subjects have a progressive CD4+ T cell loss and a wide range of immunological abnormalities, which lead to an increased risk of infections." (PMID 31382658, 2019). "This far precedes the significant loss of CD4 T cells, which becomes notable only after 1 month of infection." (PMID 30867315, 2019). "Some reports are available on the prevalence of opportunistic parasitoses among hemodialysis (HD) patients, yet there is a paucity of data on the association of CD4+ T-cell counts with such infections." (PMID 31142275, 2019). "Ces résultats divergeaient avec ceux de Bernard pour qui, les patients avec un meilleur contrôle de l'infection (CD4>350/mm3) étaient moins susceptibles d'être fumeurs réguliers (48%) que les patients avec un moins bon contrôle (53%)." (PMID 31762909, 2019). "TF viruses incorporate more envelope glycoprotein (Env) per particle compared to chronic HIV-1 viruses, which is associated with enhanced infection of target CD4 T cells." (PMID 31354736, 2019). "Using our model, we predicted the dynamics of the CD4+ T cell count and estimated the CD4+ T cell loss in the first 200 days post infection." (PMID 30931971, 2019). "C57BL/6 mice that receive a single low dose infection of T. muris are, in contrast, susceptible and develop a chronic infection associated with CD4+ Th1 cells, IFN-γ production and subsequent regulation via IL-10." (PMID 31730667, 2019). "This potential regulatory role is supported by depletion of CD4 T cells alone, which caused all mice to develop paralysis and succumb to infection." (PMID 31382545, 2019). "The early loss of gut mucosal integrity with the infection and depletion of CD4+ T cells locally is thought to facilitate the transit of bacterial components into the bloodstream." (PMID 31449552, 2019). "Administration of IFN-α2 had beneficial effects early during infection, but continued treatment ultimately led to accelerated CD4+ T cell loss, underscoring the complex relationship between type I IFN and disease progression." (PMID 31830058, 2019). "Thereafter, progressing infection results in sustained loss of these cells, except for CD4+ T cells, which only show a transient reduction following the second peak of infection (10 dpi)." (PMID 31325372, 2019). "Our data demonstrate that CXCL11 is significantly up-regulated during PHI, positively correlating with CXCL9 and CXCL10, and negatively associated with CD4+ T-cell count at 1-year-infection point." (PMID 31836011, 2019). "Only 22% of CD4-depleted mice survived to day 15 post-infection compared with 78% of control Ab-treated mice, and the CD4+ T cell-depleted animals showed greater body weight loss and more severe clinical disease scores than the control animals." (PMID 30677097, 2019). "Specifically, the frequency of CD4 TEff cells was disproportionately increased in Cacna1f–/– mice 4 weeks post-infection and demonstrates that CaV1.4 deficiency leads to a skewed T lymphocyte response." (PMID 31736943, 2019). "Poor hygienic habits, the interaction of HIV virus load and CD4+ T cell count were identified as main risk factors for infection." (PMID 31623666, 2019). "Several risk factors for severe infections have been identified, including older age at diagnosis, severe kidney involvement at diagnosis, low level of CD4+ T cell, and immunosuppressive treatment using high-dose glucocorticoid and CY." (PMID 31349802, 2019). "In this study, volunteers appeared to be protected against a homologous challenge infection with immunity associated with an IFN-γ-specific CD4+ T cell response and nitric oxide synthase (NOS) production in the absence of detectable antibodies." (PMID 30774635, 2019).